BIN1 (bridging integrator 1)
Diseases named in the same sentence as BIN1 in open-access papers (continued):
Sharing a sentence is not in itself a finding about the gene and the disease.
tumor (continued). "In particular, aberrant splicing of a brain-specific exon (exon 12A) in malignant cells can abolish the tumor-suppressor activity of BIN1 by interfering with MYC binding, which is regulated by phosphorylation of MYC at Ser62." (PMID 22248740, 2011). "Two strong candidates identified in this study are a tyrosine kinase, HCK, and a tumor suppressor, BIN1, which show upregulation at both RNA and protein levels in AHI-1-suppressed CTCL cells." (PMID 22248740, 2011). "BIN1 (Bridging integrator 1) is a ubiquitous adaptor protein with the features of a tumor suppressor mediating apoptosis by c-MYC." (PMID 17477881, 2007). "Notably, BIN-1 has also been identified as an immune-potentiating factor within the tumor microenvironment." (PMID 39859561, 2025). "Among these genes, BIN1 acts as a tumor suppressor and is dysregulated in various human cancers." (PMID 41250205, 2025). "A BIN1 inhibits tumor cell proliferation through both Myc-dependent and Myc-independent mechanisms." (PMID 40016843, 2025). "BIN1-overexpressing tumors grew more slowly than control tumors, and showed lower tumor weights." (PMID 40016843, 2025). "In addition to its Myc-dependent functions, BIN1 regulates tumor cell growth through multiple signaling pathways." (PMID 40016843, 2025). "The interaction between NS5A and BIN1 implies that HCV infection may interfere with the tumor-suppressive function of BIN1, potentially promoting the growth and proliferation of cancer cells." (PMID 37962454, 2024). "In addition, we found that SNHG10 sponged miR-200a-3p to regulate the expression of bridging integrator-1 (BIN1), a tumor-suppressor downregulated in numerous cancers." (PMID 35149697, 2022). "To confirm whether the SNHG10/miR-200a-3p/BIN1 axis exerted tumor-suppressing functions in vivo, we established a xenograft tumor mouse model." (PMID 35149697, 2022). "For example, SRSF1 regulates the alternative splicing of the tumor suppressor BIN1, which interacts with the proto-oncogene MYC to inhibit its proliferative activity, while SRSF1 overexpression endorses BIN1 exon12a inclusion that lacks tumor-suppressor activity due to reduced binding with MYC." (PMID 35027535, 2022). "Our previous research has demonstrated that SRSF1 could mediate the aberrant AS of bridging integrator-1 (BIN1) to neutralize its tumor-suppressing functions in NSCLC23." (PMID 34099633, 2021). "The BIN1 isoform is believed to function as a tumor suppressor." (PMID 33946706, 2021). "The tumor suppressor activity of BIN1 was shown to depend on the presence of MBI and MBII." (PMID 33801599, 2021). "These included cancer epigenetic targets previously implicated in tumor suppressive activity such as ANXA6 [annexin A6], VANGL2 [VANGL planar cell polarity protein 2], BIN1 [bridging integrator 1], and CREB3L1 [cAMP responsive element binding protein 3 like 1]." (PMID 34074348, 2021). "Moreover, it has been reported that CDK5 reduces the tumor inhibitory impact of BIN1 by regulating c-MYC Ser-62 phosphorylation in NSCLC." (PMID 34406978, 2021). "RNAseq analysis of distinct anatomically defined tumor regions (e.g., leading edge, infiltrating region, necrotic zone, blood vessels etc.)and in situ hybridization for BIN1 (an MG-TAM marker) or TGFBI (a BM-TAM marker), revealed tumor geographic variation in TAM composition." (PMID 33154756, 2020). "Taken above, aberrant activation of CDK5 might be able to limit the tumor suppressing effect of BIN1 by blocking the BIN1/c-MYC interaction, consequently, overcoming the overexpression of CDK5 might further improve the prognosis of NSCLC patients." (PMID 31496920, 2019). "The results demonstrated that CDK5 knockdown could restore the tumor suppressing of BIN1 by inhibiting phosphorylation of c-MYC on Ser-62." (PMID 31496920, 2019). "The patients with high expression of CDK5 and low expression of BIN1 showed similar prognosis, indicating that CDK5 could neutralize the tumor suppressing effect of BIN1 in clinical situation." (PMID 31496920, 2019).
tumor (continued). "Taken above, these results revealed that presence of CDK5 could deactivate the tumor suppressing effect of BIN1 by mediating phosphorylation of c-MYC on Ser-62." (PMID 31496920, 2019). "To explore the potential tumor suppressing mechanisms of Bin1 in ESCC, we detected the expression of the PTEN/AKT signaling pathway and found that decreased p-AKT and increased PTEN were associated with cell migration, invasion and EMT both in vitro and in vivo." (PMID 28152502, 2017). "Moreover, BIN1 is enriched in infiltrated white matter and its expression decreases rapidly in the cellular tumor." (PMID 29262845, 2017). "The results demonstrated that among the 70 tumor tissues with low Bin1 mRNA expression, the hypermethylation of Bin1 could be observed in 59 cases (92.19%), accounting for 84.29% low Bin1 protein expression." (PMID 28152502, 2017). "Furthermore, to verify the mechanisms of tumor inhibition by Bin1 in vivo, we detected the expression alterations of MMP-2, E-cadherin and BCL-2 in tumor-bearing mice using IHC." (PMID 28152502, 2017). "However, abnormal splicing of BIN1 can generate the BIN1 +12A which lacks the tumor suppressor activity." (PMID 26273588, 2015). "Indeed, the observed enhancement in tumor growth following Bin-1 deletion was reversed in the presence of the 1-methyltryptophan (1-MT) IDO inhibitor only in the setting of an intact immune system." (PMID 25339948, 2014). "While in preclinical models the induction and expression of IDO is controlled by tumor suppressor genes such as Bin-1 and oncogenes such as c-kit, respectively, the molecular mechanisms that drive constitutive IDO expression in human tumors are incompletely understood." (PMID 24657910, 2014). "Notably, only nuclear-localizing isoforms of BIN1 have tumor suppressor activities that can restrict proliferation, survival, and immune escape of oncogenically transformed cells." (PMID 22248740, 2011). "BIN1 encodes several isoforms of a nucleocytoplasmic adaptor protein, one of which was initially identified as a MYC-interacting protein with features of a tumor suppressor." (PMID 21143783, 2010). "Furthermore, circPDK1 functions as a scaffold to enhance the interaction between 65 kDa Myc box-dependent interacting protein 1 (BIN1), a tumor suppressor that interacts with c-myc to limit its transcriptional activity, and UBE2O, thereby facilitating BIN1 degradation by UBE2O." (PMID 40004471, 2025). "Furthermore, we demonstrated that BIN1 loss inhibits CD8+ T cell infiltration by stabilizing G3BP1, which in turn induces the establishment of an immunosuppressive microenvironment and facilitates tumor progression." (PMID 40346580, 2025). "Although the pro-apoptotic BIN1 tumor suppressor facilitates cisplatin sensitivity but is missing in various human cancer cells in vitro, little is known about whether (and how) BIN1 could be restored in cisplatin-refractory cancer cells." (PMID 34948122, 2021). "Thus, BIN1 exerts also its tumor suppression activity by Myc-independent mechanisms that could be linked to cytoplasmic and/or nuclear actin cytoskeleton regulation via its SH3 domain, as reported for BIN1 muscular functions." (PMID 32164332, 2020). "Interestingly, Myc-independent BIN1 activity in tumor suppression has also been reported." (PMID 32164332, 2020). "Thus, the presence of the factors inducing phosphorylation of c-MYC on Ser-62 could deactivate the tumor suppressing effect of BIN1." (PMID 31496920, 2019). "Furthermore, with Co-IP experiment, we found that CDK5 was correlated with the anergy of BIN1/c-MYC interaction, suggesting that CDK5 could neutralize the tumor-suppressing effect of BIN1 via inducing phosphorylation of c-MYC at Ser-62 site." (PMID 31496920, 2019). "Therefore, the tumor-side injection of DAC could restore Bin1 expression and inhibit the carcinogenesis of ESCC in null mice." (PMID 28152502, 2017).
tumor (continued). "Bridging integrator 1 (BIN1), a well-characterized tumor suppressor that interacts with and inhibits oncogenic Myc transcription factors, has demonstrated crucial roles in various cancer types." (PMID 40016843, 2025). "Compared to the BIN1-WT group, the proportion of CD8+ T cell infiltration in tumor tissues was increased in the BIN1-WT + SB02024 group, while the proportion of CD8+PD-1+TIM3+ T cell infiltration was reduced." (PMID 40346580, 2025). "Consistent with prior studies, our results revealed that knocking out BIN1 in tumor cells significantly enhances the development of NSCLC both in vitro and in vivo, underscoring the role of reduced BIN1 expression in driving cancer progression." (PMID 40346580, 2025). "RNA-seq analysis of BIN1-KO cells and tumors revealed a marked downregulation of STAT1 and its downstream chemokines in both BIN1-KO cells and tumor tissues." (PMID 40346580, 2025). "Because ALDH1 promotes tumor progression through NOTCH signaling, we investigated the interactions between BIN1 and these molecules in BLCA." (PMID 40016843, 2025). "Our research shows, for the first time, that BIN1 is underexpressed in BLCA and functions as a tumor suppressor gene." (PMID 40016843, 2025). "Correspondingly, compared with the BIN1-KO group, the BIN1-KO + sh-G3BP1 group exhibited a significantly reduced positive rate of G3BP1 expression in tumor tissues, whereas the positive rate of STAT1 expression was markedly increased." (PMID 40346580, 2025). "The BIN1 MBD interacts with the c-MYC transcription factor, functioning as a tumor suppressor, with BIN1 protein levels altered in several cancer types and correlated with increased cancer metastasis." (PMID 40835006, 2025). "In syngeneic mouse models, the knockout of BIN1 in NSCLC cells significantly inhibited CD8+ T cell infiltration and impaired their cytotoxic function, facilitating tumor immune evasion." (PMID 40346580, 2025). "SNHG10 acted as a tumor-suppressor to inhibit tumorigenesis and EMT of EOC by regulating miR-200a-3p/BIN1." (PMID 35149697, 2022). "BIN1 is a well-recognized tumor suppressor among the SRSF1 target genes, which is lost in several NSCLC, and restored expression of BIN1 can suppress malignant phenotypes." (PMID 35027535, 2022). "RBM25 acts as a tumor suppressor and regulator of MYC activity by controlling the splicing of the MYC inhibitor BIN1." (PMID 36147313, 2022). "Some of the tumor suppressors and oncogenes regulated by HNRNPA2B1 include c-FLIP, BIN1, and WWOX, and the proto-oncogene RON." (PMID 33163396, 2020). "The expression of methylated Bin1 was significantly related with the TNM stage, tumor differentiation grade, invasion range, and lymph node metastasis status but not with gender and age." (PMID 28152502, 2017). "For example, the genes MacroH2A, IGFR, BIN1, PKM, MKNK2, S6K1 and TNC have been verified to be differentially spliced in cancer, and to have an important role in tumor initiation and progression." (PMID 25908786, 2015). "Similar to BIN-1, COX2, and TβRIII above, this work implicates Wnt5a as a factor with dual roles in carcinogenesis including tumor invasion and metastasis, as well as the suppression of local immune surveillance." (PMID 25339948, 2014). "In conclusion, the present study showed aberrant tumor-specific methylation alterations for APC, BIN1, BMP6, BRCA1, CST6, ESR-b, GSTP1, P14, P16, P21, PTEN and TIMP3 in the studied cohort." (PMID 22695536, 2012). "Two-way hierarchical clustering in serum and tumor tissue showed significant hypermethylation patterns of seven genes (APC, BIN1, BMP6, BRCA1, CST6, P16 and TIMP3) compared with normal tissue." (PMID 21283676, 2011). "Hierarchical clustering showed significant hypermethylation patterns for serum and tumor tissue compared with normal tissue for seven genes (APC, BIN1, BMP6, BRCA1, CST6, P16 and TIMP3)." (PMID 21283676, 2011).
tumor (continued). "To further evaluate whether host BIN1 influenced the TME, we analyzed tumor-infiltrating immune cells in detail." (PMID 40346580, 2025). "When comparing UMUC-3 cells with and without BIN1 overexpression, Myc depletion reduced tumor sphere-formation significantly." (PMID 40016843, 2025). "This indicates that BIN1 within the TME-not just within tumor cells—plays a critical role in promoting NSCLC progression." (PMID 40346580, 2025). "BIN1 overexpression correlated with reduced expression of key stemness and EMT markers, including Myc, ALDH1, OCT4, EPCAM, KLF4, NANOG, SOX2, and decreased tumor sphere-formation capabilities, suggesting EMT inhibition." (PMID 40016843, 2025). "Exosomal circPDK1 acts as a scaffold to enhance the interaction between ubiquitin conjugating enzyme E20 (UBE2O) and bridging integrator 1 (BIN1), and it induces UBE2O-mediated degradation of BIN1, a protein that inhibits tumor progression by suppressing c-myc transcriptional activity." (PMID 37753074, 2023). "The SNHG10 expression in the tumor tissues with positive expression of BIN1 was significantly higher, than that in the tissues with negative expression of BIN1, indicating that SNHG10 was positively correlated with BIN1 (P < 0.001)." (PMID 35149697, 2022). "To preliminarily clarify whether presence of CDK5 could act as tumor promoter by effecting the interaction of BIN1/c-MYC, we detected both CDK5 and BIN1 expression status in NSCLC cells." (PMID 31496920, 2019). "The investigation of IDO expression in tumor cells showed that, IDO overexpression into tumor cells is controlled by Bin1 (tumor suppressor gene), while this gene becomes disabled during tumor development for unknown reasons yet9." (PMID 29959375, 2018). "Our group has previously shown that BIN1, originally identified as a MYC-interacting tumor suppressor, functions as a cellular inhibitor of PARP1 in vitro and that MYC induces cisplatin resistance by liberating intrinsic PARP1 activity through directly suppressing BIN1 levels." (PMID 28590415, 2017). "The quantitative DNA methylation analysis of the candidate genes showed higher methylation proportion in the primary tumor tissue than that of the matched normal tissue and the differences were significant for the APC, BIN1, BMP6, BRCA1, CST6, ESR-b, P16, PTEN and TIMP3 promoter regions (P<0.05)." (PMID 22695536, 2012). "Tumor-specific isoforms of BIN1, including exon 12A, are not able to interact with MYC because an intramolecular interaction occurs between the consensus class I SH3-binding domain, encoded by exon 12, and the SH3 domain, preventing MYC from binding to the SH3 domain of BIN1." (PMID 33801599, 2021). "As BIN1 has been proved to play a pivotal role in proliferation, invasion and migration abilities of cancer cells, we then detected whether CDK5 could affect these malignant behaviors by inhibiting the tumor suppressing effect of BIN1." (PMID 31496920, 2019). "However, a frequent phosphorylation of c-MYC at Ser-62 site could block the BIN1/c-MYC interaction and limits the tumor-suppressive effect of BIN1." (PMID 31496920, 2019). "However, the methylation status of Bin1 in ESCC remains unclear; hence the effect of Bin1 methylation on ESCC carcinogenesis and tumor progression is also unknown." (PMID 28152502, 2017). "After noting that BIN-1 seemed to suppress the development of a transformed epithelial tumor model via an immune-dependent mechanism, Muller and colleagues noted that the deletion of Bin-1 significantly enhanced the IFN-γ-mediated upregulation of IDO expression by tumor cells." (PMID 25339948, 2014).
cancer (42 papers, 2007 to 2025). A tumor composed of atypical neoplastic, often pleomorphic cells that invade other tissues. "Mounting evidence underscores the strong association between aberrant BIN1 expression and cancer development." (PMID 40346580, 2025). "The loss of the BIN1 tumor suppressor is among the most common oncogenic drivers across various cancers, including esophageal, gastric, neuroblastoma, breast, lung, colorectal, prostate, pancreatic cancers, and malignant pleural mesothelioma." (PMID 40346580, 2025). "We also observed that the cisplatin sensitivity restored by si-MDC1 in BIN1-deficient cancer cells was compromised by carbobenzoxy-valyl-alanyl-aspartyl fluoromethyl ketone (z-VAD-fmk) (20 μM), a cell-permeable pan-caspase inhibitor." (PMID 34948122, 2021). "As predicted, PARP1, one of the most representative cellular substrates of caspase-3 during apoptosis, was cleaved when si-MDC1 was transfected in BIN1-deficient cancer cells in the presence of cisplatin." (PMID 34948122, 2021). "As expected, the cisplatin sensitivity induced by si-RNF8 was significantly compromised by a pan-caspase inhibitor z-VAD-fmk (20 μM) or si-Caspase-3 in BIN1-deficient cancer cells." (PMID 34948122, 2021). "Collectively, these results suggest that RNF8 physically binds to and protects ATM-phosphorylated MDC1 from caspase-dependent proteolytic cleavage in BIN1-deficient cancer cells." (PMID 34948122, 2021). "c-Myc expression has also been associated with platinum resistance in various cancer types for example via repression of c-MYC inhibitor bridging integrator 1 or increased platinum accumulation in cells." (PMID 27191653, 2016). "We next investigated whether MDC1, immediately downstream of γH2AX, determines cisplatin resistance in BIN1-deficient cancer cells." (PMID 34948122, 2021). "Conversely, BIN1 deficiency often accompanies cancer chemoresistance." (PMID 34948122, 2021). "Re-introducing BIN1 causes cancer cells to undergo caspase-independent apoptosis." (PMID 33801599, 2021). "Therefore, it is reasonable to speculate that a BIN1 loss somehow activates cellular mechanisms vital for cancer-cell survival in the presence of genotoxic therapeutics, such as cisplatin." (PMID 34948122, 2021). "Experimental validation confirmed that BIN1 suppresses cancer cell proliferation, migration, invasion, and stem cell characteristics by targeting ALDH1." (PMID 40016843, 2025). "Researchers utilized a modified Cre-lox technique to generate BIN1 chimeric mice and documented the incidence of various cancer types." (PMID 40346580, 2025). "Bin1 can downregulate IDO1 through STAT1 and NF-κB-dependent pathways; however, in many cancers, Bin1 is inactivated, supporting IDO1 overexpression." (PMID 41035912, 2025). "Nevertheless, the specific role and pattern of BIN1 expression in the pathogenesis of human cancers, especially BLCA, remain largely unexplored." (PMID 40016843, 2025). "BIN1 overexpression inhibited cancer cell proliferation by promoting apoptosis and suppressed epithelial-mesenchymal transition (EMT), thereby reducing local invasion and distant metastasis." (PMID 40016843, 2025). "BIN1 also plays a crucial role in inhibiting immune evasion in cancer cells by suppressing the STAT1 and NF-κB pathways, which in turn reduces the expression of the immunoregulatory enzyme IDO." (PMID 40346580, 2025). "The classical role of BIN1 in cancers is suppressing c-Myc’s function and activating caspase-independent cell death." (PMID 35149697, 2022). "One is the PARP1-MYC pathway for BIN1 reduction, which spontaneously emerges when cancer cells become cisplatin-resistant, and the other is the ATM-phosphorylated MDC1-RNF8 signaling pathway by a BIN1 loss." (PMID 34948122, 2021).